ANKRD13D (ankyrin repeat domain 13D)
Description:
Ubiquitin-binding protein that specifically recognizes and binds 'Lys-63'-linked ubiquitin. Does not bind 'Lys-48'-linked ubiquitin. Positively regulates the internalization of ligand-activated EGFR by binding to the Ub moiety of ubiquitinated EGFR at the cell membrane.
Tractability: Antibody: UniProt places it where antibodies can reach, with high confidence; its Gene Ontology location is reachable by antibodies, with high confidence. PROTAC: ubiquitination databases record sites on it; its protein half-life has been measured.
Gene: Protein-coding gene on chromosome 11 (67,289,291 to 67,302,486, forward strand). Ensembl gene ENSG00000172932.
Subcellular location: Cell membrane; Late endosome
Gene Ontology:
Molecular function: protein binding; ubiquitin-modified protein reader activity
Biological process: negative regulation of receptor internalization; regulation of receptor-mediated endocytosis
Cellular component: cytoplasm; perinuclear region of cytoplasm; plasma membrane; late endosome
Genetic constraint (gnomAD): Loss-of-function variants: 25 observed, 63.22 expected, observed/expected ratio (o/e) 0.4, 90% interval 0.29 to 0.55. The upper end of that interval is the gene's LOEUF score, 0.55, which puts it in group 2 of 6, group 1 being the genes least tolerant of losing a copy. Missense variants: 735 observed, 791.02 expected, observed/expected ratio (o/e) 0.93, 90% interval 0.87 to 0.99. Synonymous variants: 331 observed, 318.9 expected, observed/expected ratio (o/e) 1.04, 90% interval 0.95 to 1.14.
Homologues: Orthologues: macaque ANKRD13D (98% identical), chimpanzee ANKRD13D (97% identical), guinea pig ANKRD13D (95% identical), pig ANKRD13D (94% identical), dog ANKRD13D (94% identical), rat Ankrd13d (93% identical), mouse Ankrd13d (92% identical), zebrafish ankrd13d (71% identical), Drosophila melanogaster CG15118 (45% identical), Caenorhabditis elegans C18F10.7 (35% identical). Paralogues in human: ANKRD13B (65% identical), ANKRD13A (53% identical), ANKRD13C (27% identical).
Diseases named in the same sentence as ANKRD13D in open-access papers:
ANKRD13D is named in the same sentence as 1 disease in open-access papers, as found by Europe PMC text mining. Sharing a sentence is not in itself a finding about the gene and the disease. The quoted sentences say what the papers report.
Alzheimer disease (1 paper, 2025). A progressive, neurodegenerative disease characterized by loss of function and death of nerve cells in several areas of the brain leading to loss of cognitive function such as memory and language. "A recent whole-genome sequencing study revealed that ANKRD13D, a member of the ANKRD13 family that shared high sequence homology and overlapping functions with ANKRD13A, is associated with the risk and progression of Alzheimer’s disease (AD)." (PMID 40975168, 2025).